IL17RA (interleukin 17 receptor A)
Diseases named in the same sentence as IL17RA in open-access papers (continued):
Sharing a sentence is not in itself a finding about the gene and the disease.
infection (continued). "Indeed, as we have seen in numerous prior studies, 5 days post infection IL-17RA-/- mice exhibited a high fungal burden (~1x104 CFU/g tissue) and showed a 20% weight loss, validating the importance of IL-17RA signaling in protection against OPC." (PMID 25849644, 2015). "As previously published with IL-17RA−/− mice, we found that the IL-17−/− mice are not more susceptible than B6 mice to low dose aerosol Mtb H37Rv infection, at either early or later time points." (PMID 24831696, 2014). "IL-17RA-deficient mice are vulnerable to infections caused by extracellular pathogens, though no data concerning the cornea are available." (PMID 23378722, 2013). "Our results underscore the role of IL-17RA in the modulation of IFN-γ-mediated inflammatory responses during infections and uncover a previously unrecognized regulatory mechanism that involves the IL-17RA-mediated recruitment of suppressive IL-10-producing neutrophils." (PMID 22577359, 2012). "However, significantly increased IL-17A+/CD3+ and IL-17A+/γδ+ T cell populations were also observed in the lungs of IL-17RA−/− mice compared to wild-type mice on day 7 post-infection." (PMID 23216912, 2012). "We determined that both chemokines were clearly induced by T. cruzi infection in the spleen and liver of WT mice but, throughout the infection period evaluated or at least during the peak of the infection (day 20 post-infection), showed reduced concentration in the same tissues from IL-17RA KO mice." (PMID 22577359, 2012). "Our results underscore the role of IL-17RA in the modulation of IFN-γ-mediated inflammatory responses during infections and uncover a previously unrecognized regulatory mechanism that likely involves IL-17 family-mediated recruitment of suppressive neutrophils." (PMID 22577359, 2012). "In a second approach, we analyzed Il17ra induction during infection." (PMID 21124903, 2010). "Nevertheless, overall these data demonstrated that IL-17RA deficiency did not affect inflammatory pathology and mucosal chemokine/cytokine induction at 12 h post infection." (PMID 21124903, 2010). "To determine if loss of DETC combined with impaired IL-17 signaling might promote susceptibility to staph infection, we depleted DETC from IL17RA KO mice and found that the combined loss of DETC and impaired IL-17 signaling leads to an impaired clearance of the infection." (PMID 37691956, 2023). "The authors would like to thank Jay K. Kolls (Center for Translational Research in Infection and Inflammation, Department of Pediatrics and Department of Medicine, Tulane University School of Medicine, New Orleans, Louisiana, USA) and Amgen Inc. for providing Il17ra–/– mice." (PMID 37937643, 2023). "Intracellular cytokine staining revealed that while γδ T cells were the main source of IL-17 during infection, the proportion of cells producing IL-17 was actually diminished by B. abortus infection, which may explain while IL-17Ra was dispensable for protection." (PMID 21765931, 2011). "The increased damage to the tongue tissue also correlated with fungal susceptibility, as Il17ra−/− HNI + OPC mice had higher tissue fungal burden on Day 4 following infection compared to WT HNI + OPC mice and Il17ra−/− +OPC-only mice." (PMID 35628751, 2022). "As expected and consistent with the proviral role of IL-17RA signaling, MHV68 infection triggered an increase in MHV68-specific CD4 T cell population expressing IL-17A following ex vivo restimulation with immunodominant MHV68 epitopes." (PMID 33824206, 2021). "Despite the assumption that neutrophil infiltration is controlled by IL-17RA in OPC, recent findings show IL-1R signaling regulates fungal clearance via infiltration of neutrophils to the infection site." (PMID 29371568, 2017). "Expression of the chemokine Cxcl5 was impaired in the absence of either IL-1R or IL-17RA signaling, suggesting a role in both activation and maintenance of the neutrophil population during infection." (PMID 42085507, 2026).
infection (continued). "Regarding parasitic diseases, the IL-17RA coding gene was down-regulated in grouper upon infection with Cryptocaryon irritans, but not the rest of IL-17 receptors." (PMID 38827125, 2024). "Based on the pathologist’s scoring, there were no neutrophils recruited to the gastric mucosa of InsGAStg/tgIl17ra-/- mice; in the absence of IL-17RA they do not develop acute inflammation (6 weeks post-infection)." (PMID 39588838, 2024). "Similar to what we saw in a subset of DKO mice, we found that the infection in some IL17RA KO depleted for DETCs shifted from the initial site of infection on the upper back to the face region (not shown)." (PMID 37691956, 2023). "We first tested if the absence of IL-17RA or IL-17RC blocks CNS demyelination following infection with the HSV-IL-2 virus." (PMID 36817487, 2023). "We confirm in our experimental model previous observations showing that early infection control in the lung is dependent on IL-17RA but not of IFNγR." (PMID 35771771, 2022). "Wild-type, IL-17RA-/- and asthmatic C57BL/6 mice were intranasally infected with 5x106 CFU of our B. melitensis 16M mini-Tn5 mutant library and sacrificed at 48 hours post-infection." (PMID 35771771, 2022). "Then, in the absence of IL-17RA, damage and fungal burden were elevated after irradiation and infection compared to control mice." (PMID 35628751, 2022). "Comparison of the CFU counts at 48 hours post-infection showed that IL-17RA-/- mice and asthmatic mice, but not TNFR1α-/-, IL-4-/- and IFNγR-/- mice, lose control of early B. melitensis infection." (PMID 35771771, 2022). "To test our Tn-seq predictions, we compared the course of ΔwbkF and Δper (LPS O chain biosynthesis) and ΔfadA and ΔfadJ (β-oxidation of fatty acids) with a wild-type B. melitensis strain in wild-type, IL-17RA-/- and asthmatic mice, by counting the CFU 5 and 48 hours post-infection." (PMID 35771771, 2022). "WT mice exposed to HNI + OPC had increased neutrophils in circulation, while Il17ra−/− mice did not have a similar increase in neutrophils in the blood after radiation and infection." (PMID 35628751, 2022). "Notably, we find that IL17RA physically binds to SARS-CoV-2 ORF8, and genetic disruption results in decreased infection." (PMID 33060197, 2020). "More surprisingly, Brucella control in the lesion required IL-17RA, whereas it was not necessary for control of the primary infection." (PMID 31354728, 2019). "When neutrophil levels are depleted further in the Il17ra KO animals, they are no longer able to restrict the infection and animals thus develop severe disease and die." (PMID 29813133, 2018). "There was a clear and significant difference in survival between WT and Il17ra KO animals, with none of the Il17ra KO animals dying following infection, compared to a 40% mortality in the WT animals." (PMID 29813133, 2018). "Even at higher infection doses, the combined absence of the IL-17RA and IL-22 pathways did not profoundly compromise the control of chronic M. tuberculosis infection, which argues against major compensation between the two pathways in this model." (PMID 27853279, 2016). "Although in TNFα-deficient mice lung infiltrating cells showed an increased granulocytic CD11b+Ly6G+ cell response, the absence of IL-17RA and/or IL-22 had little influence on CD11b+Ly6G+ cells one month post-infection." (PMID 27853279, 2016). "In striking contrast to the results of infection with the YH5 strain, infection of IL-17RA knockout animals with the NH57388A P. aeruginosa strain resulted in the death of all infected animals within 3 days of infection, a statistically significant difference from WT littermates." (PMID 27698020, 2016). "Stimulation of PBMC with Echinococcus multilocularis vesicle (EmV) antigen for 24 hours did not result in cellular production differences of soluble IL-17RA between AE patients and infection-free control groups." (PMID 22969818, 2012).
infection (continued). "Spread to mLN was not significantly affected in any of the groups, indicating that dissemination to deeper sites of the GALT was not affected in the Il17ra−/− mice at this early stage of the infection (p≥0.05)." (PMID 21124903, 2010). "The lack of B-1a and B-1b B cells expansion in the spleen and peritoneal cavity during MHV68 infection could be due to the lack of NF-kB activity downstream of IL-17RA signaling in those cells." (PMID 41335125, 2025). "Interestingly, loss of B cell-specific IL-17RA signaling had no impact on the humoral response to MHV68 infection at 16 and 42 days post-infection, despite the attenuated germinal center response." (PMID 41335125, 2025). "Thus, B cell-intrinsic IL-17RA signaling helps promote peak MHV68 latency at 16 days post-infection but does not impact the long-term maintenance of the latent viral reservoir." (PMID 41335125, 2025). "In the same study, infection of moMΦ with Georgia 2007 strain down-regulated other receptors, such as interferon receptors (IFNAR1, IFNAR2, IFNGR) and interleukin receptors (IL4R, IL10RA, IL10RB, and IL17RA), as well as transcriptomic factors (e.g., FOS, JUN, and TBK1)." (PMID 40530033, 2025). "IL-17RA was up-regulated only on day 3 post infection, but not thereafter." (PMID 37270623, 2023). "However, IL-17RA KO mice failed to reduce the parasite burden at later stages of infection, as attested by the increased parasite load in the spleen at 22 and 130 days post-infection (dpi)." (PMID 30364284, 2018). "Interestingly, some genes implicated in LPS synthesis, such as wbkF and per, which could also be involved in the biosynthesis of native hapten, are indispensable in vivo at 48 hours post-infection in wild-type mice but not in IL-17RA-/- mice." (PMID 35771771, 2022). "On the basis of marked difference between WT and IL-1R−/− mice, we speculate that IL-17 plays a non-redundant role in survival after C. neoformans 52D infection; however, studies of BALB/c mice that are deficient for IL-17 or IL-17RA would be required to formally test this hypothesis." (PMID 29403476, 2017). "Given that plasma cells support the majority of MHV68 reactivation from wild-type splenocytes and ubiquitous expression of IL-17RA, these data suggest that IL17A proviral effects on MHV68 infection are not restricted to a single cell type." (PMID 33824206, 2021). "In this context, our data provide evidence that a PD-L1 checkpoint blockade at the CD8+ T cell expansion phase not only restored resistance to T. cruzi absence of IL-17RA signaling, but also boosted protective CD8+ T cell immunity during the natural infection." (PMID 30364284, 2018). "Three weeks post infection, intestinal tissue samples were collected for RNA-sequencing, with samples from uninfected C57BL/6 WT and C57BL/6 IL-17RA KO animals serving as negative controls." (PMID 28819174, 2017). "In addition, IL-17A has been reported to be required for the development of cytotoxic and humoral responses, therefore parasite-specific adaptive immune responses may be undermined in T. cruzi infected mice lacking IL-17RA signaling contributing to reduced resistance to infection." (PMID 22577359, 2012).
cancer (40 papers, 2013 to 2026). A tumor composed of atypical neoplastic, often pleomorphic cells that invade other tissues. "Statistical analysis demonstrated that the cancer cell line was more susceptible to decreased expression of IL17RA." (PMID 36009523, 2022). "IL-17RA plays a significant role in cancer by mediating the effects of IL-17, a proinflammatory cytokine." (PMID 41438576, 2026). "In our unpublished data indicates the IL‐17RA overexpression promotes cancer stem‐like properties of CRC cells by Stat3 activation." (PMID 38491831, 2024). "We provide evidence that IL-17RA plays a cancer suppressive role through regulating the adaptive immune response to H. pylori." (PMID 39588838, 2024). "IL-17A and IL-17RA are members of a large family of IL-17 cytokines that have been demonstrated to have both pro-cancer (in most cases) and cancer-inhibiting effects." (PMID 37760548, 2023). "We assessed the expression levels of IL-17A and IL-17RA in cancer cells in prostate and, for the first time, also in LN+." (PMID 37760548, 2023). "IL-17RA is necessary to prevent severe damage and promote healing after ionizing radiation, and this important contribution has implications for cancer therapies related to the Th17 pathway." (PMID 34220843, 2021). "Strong correlations have been found between IL-17RA, microbiota, and cancer, and most of them have been attributed to IL-17A." (PMID 33244315, 2020). "More importantly, we demonstrated that circulating level of IL-17A as well as the contents of IL-17A and IL-17RA in local cancer tissues were significantly increased in TSCC patients." (PMID 28035060, 2017). "IL-23A was secreted from both macrophages and GC cells and promoted cancer proliferation through IL-17A/IL-17RA/NF-κB signaling." (PMID 25349535, 2014). "However, the specific mechanisms by which IL-17RA contributes to cancer stemness remain poorly understood." (PMID 41438576, 2026). "Ultimately, the data presented herein suggest that IL-17RA plays a regulatory role in the gastric mucosa during H. pylori infection, mitigating the development of gastric pathologies including the lymphoid follicles, dysplasia, and cancer." (PMID 39588838, 2024). "Both IL-17RA and IL-17RC play essential roles in disease progression including cancer." (PMID 33802737, 2021). "Brodalumab, a monoclonal antibody against IL-17RA is also under investigation in patients affected by rheumatoid and psoriatic arthritis, and it might also find application in cancer patients." (PMID 33244315, 2020). "Therefore, understanding the context in which IL-17 signaling through IL-17RA may be protective is critical as we consider immunotherapeutics for the treatment of cancer and other inflammatory diseases." (PMID 39588838, 2024). "IL-17RA is one of the members of the IL-17 receptor family (IL17RA-IL17RE), and plays a vital role in cellular processes, including inflammation and cancer cells." (PMID 37637418, 2023). "We found that the inhibition of IL17RA and PLK4 significantly blocked the proliferation of normal keratinocytes and SCC cancer cells in in vitro studies." (PMID 36009523, 2022). "Further clinical studies are needed to prove the therapeutic effects of CMP in cancer patients, particularly in whom EGFR and IL-17RA play a pivotal role." (PMID 29212184, 2017). "Although previous research has implicated STAT3 in the regulation of stemness and IL-17 signaling in cancer, the direct mechanistic connection between IL-17RA and STAT3-mediated CSC properties had not been demonstrated." (PMID 41438576, 2026).
cancer (continued). "Given the high levels of inhibitory receptors in CD8+ T cells elicited by T. cruzi infection in absence of IL-17RA, it is likely that the combination of different checkpoint Abs may have a stronger effect in these settings, as reported in cancer models." (PMID 30364284, 2018).
bacterial infection (5 papers, 2021 to 2025). "Analysis of proinflammatory cytokines and chemokines at different time points showed significant upregulation of Tnf, Mmp14, Il1b, Il1a, Il17ra, Cxcl1, Cxcl2, Ccrl2, Ccl3, Ccl4, and Ccl9 after bacterial infection." (PMID 41117166, 2025).
inflammation (5 papers, 2011 to 2022). Aberrant reaction of the microcirculation characterized by movement of fluid and leukocytes from the blood into extravascular tissues. "Although current studies have noticed the significant role of IL-17RA-mediated inflammatory response in chronic hepatic inflammation, the exact molecular mechanisms underlying the increase of IL-17RA remains largely enigmatic." (PMID 36172147, 2022). "Our study showed for the first time that IL-23p19 and IL-17RA signaling were necessary to trigger late pulmonary inflammation and fibrosis and confirmed by IL-17A neutralization that IL-17A is required for late disease." (PMID 21858022, 2011). "Therefore, further studies are needed to explore the mechanism that the decreased m6A mRNA methylation of the IL-17RA resulted in the increased protein level of IL-17RA in chronic hepatic inflammation." (PMID 36172147, 2022). "Also, following i.n. challenge with PR8, IL-17RA-/- mice show reduced levels of the oxidized phospholipids that are critical mediators of acute lung inflammation, and have better survival rates than the wild type controls." (PMID 24073225, 2013).
cardiovascular diseases (3 papers, 2022 to 2025). "The role of genetic knockout mouse models of IL-17A and IL-17RA in cardiovascular diseases has been investigated in literature." (PMID 40276600, 2025). "Regarding the use of these mouse models in studies on CMs, there was not explicitly mentioned that have utilized IL-17A or IL-17RA genetic knockout mouse models specifically for investigating the effects of CMs on cardiovascular diseases." (PMID 40276600, 2025).
infectious disease (2 papers, 2012 to 2017). A disorder directly resulting from the presence and activity of a microbial, viral, or parasitic agent in humans. "There were significant increases in the IL-17RA knockout animals in mapped genes belonging to the Glycan biosynthesis and metabolism and Infectious Diseases: Bacterial categories, with significant reductions in three other categories as shown." (PMID 29058583, 2017).
liver (2 papers, 2013 to 2022). "However, we also detected milder expression of IL-17RA in NK cells, and therefore can't exclude the possibility that IL-17 may also exacerbate PolyI:C-induced liver damage through acting directly on NK cells." (PMID 24069246, 2013).
genodermatosis (1 paper, 2020). "Interestingly our study revealed interleukin 17 receptor A (IL17RA) as a new gene involved in a recessively inherited genodermatosis of Holstein cattle." (PMID 32448141, 2020).
kidney disease (1 paper, 2024). "We did not observe any relationship between the selected SNPs in genes coding for IL-17A, IL-17RA, IL-17RC, and miR-146a-5p and kidney disease risk, as their alleles/genotypes segregated similarly in patients and controls." (PMID 38792460, 2024).
IL17RA also shares sentences with these, for which no sentence is quoted: ankylosing spondylitis (12 papers); atherosclerosis (4); Sepsis (4); Autosomal dominant hyper-IgE syndrome (3); idiopathic pulmonary fibrosis (3); liver disease (3); alcoholic liver diseases (2); autism (2); bacterial pneumonia (2); benign prostatic hyperplasia (2); bullous pemphigoid (2); Cirrhosis (2); Cognitive impairment (2); colon cancer (2); diabetes (2); epilepsy (2); experimental autoimmune encephalomyelitis (2); glioblastoma (2); hepatocellular carcinoma (2); Hyperinsulinemia (2); Insulin resistance (2); intestinal inflammation (2); malaria (2); metabolic syndrome (2); multiple sclerosis (2); non-alcoholic fatty liver disease (2); non-small cell lung carcinoma (2); stomach cancer (2); uveitis (2); vasculitis (2).
A further 104 diseases each share a sentence with IL17RA in 1 paper.